SCHLAP1 (SWI/SNF complex antagonist associated with prostate cancer 1)
Synonyms: PCAT11; LINC00913; PCAT114
Gene: Long non-coding RNA gene on chromosome 2 (180,692,009 to 180,916,939, forward strand). Ensembl gene ENSG00000281131.
Diseases named in the same sentence as SCHLAP1 in open-access papers:
SCHLAP1 is named in the same sentence as 17 diseases in open-access papers, as found by Europe PMC text mining. Sharing a sentence is not in itself a finding about the gene and the disease. The quoted sentences say what the papers report.
prostate carcinoma (62 papers, 2014 to 2025). A carcinoma that arises from epithelial cells of the prostate gland. "SChLAP1 is markedly overexpressed in aggressive prostate cancer and has been implicated in promoting the metastatic progression of the disease." (PMID 39975023, 2025). "It was reported that SCHLAP1 is associated with the development of prostate cancer, according to various articles." (PMID 38605206, 2024). "The long noncoding RNA known as SChLAP1, which stands for second chromosomal locus associated with prostate is significantly expressed in twenty-five percent of prostate cancer cases." (PMID 39512820, 2024). "SChLAP1 is another up-regulated lncRNA in prostate cancer whose up-regulation is associated with poor patient outcomes, such as metastases and prostate cancer specific mortality." (PMID 37025585, 2023). "Other lncRNAs have been suggested as prognostic markers for prostate cancer, e.g., SChLAP1 that is associated with metastasis occurrence, or lung carcinoma, e.g., HOTAIR for small cell lung cancer, which associate with lymphatic invasion and relapse." (PMID 37143733, 2023). "Second chromosome locus associated with prostate-1 (SChLAP1), which is associated with poor prognosis and metastatic progression in prostate cancer, promotes prostate cancer invasion and metastasis by disrupting the activity of the SWI/SNF complex." (PMID 33435206, 2021). "We revealed that the lncRNA SChLAP1 (second chromosome locus associated with prostate-1) promotes prostate cancer development via interacting with EZH2 to promote H2K27me3 and regulate miR-340-5p/miR-143-3p/miR-145-5p expression." (PMID 33589600, 2021). "The lncRNA SChLAP1 is a tissue biomarker that can be used to identify prostate cancer patients at high risk of fatal progression, according to a study of prostate cancer patients in the United States." (PMID 34262591, 2021). "This study aimed to investigate the mechanism of SChLAP1 (second chromosome locus associated with prostate-1) on microRNA expression in prostate cancer." (PMID 33589600, 2021). "SCHLAP1 is a biomarker to predict metastasis development and to discriminate high-risk from low-risk prostate cancer and its dysregulation was found to be associated with aggressive intraductal and cribiform pathology of prostate cancer." (PMID 31366128, 2019). "lncRNA SChLAP 1 (Second Chromosome Locus Associated with Prostate 1 or known as LINC00913) has been reported to be highly expressed in patients with prostate cancer after microarray analysis of 960 prostate cancer tissue samples." (PMID 30200254, 2018). "The annotated ones include SChLAP1, an lncRNA known to be associated with aggressive prostate cancers." (PMID 29723810, 2018). "One such lncRNA is called Second Chromosome Locus Associated with Prostate 1 (SChLAP1), which is overexpressed in a subset of prostate cancers." (PMID 28212646, 2017). "The majority of biomarker lncRNAs reported by now are derived from researches based on particular type of cancer, such as SChLAP1 to be identified as a prostate cancer–associated lncRNA." (PMID 26812883, 2016). "SChLAP1 expression increased with prostate cancer progression, and a high level of SChLAP1 was associated with poor outcome among patients with clinically localized prostate cancer after radical prostatectomy." (PMID 26110379, 2015). "SChLAP1, second chromosome locus associated with prostate-1, is a long noncoding RNA that is frequently over-expressed in aggressive prostate cancers." (PMID 26110379, 2015). "Similarly, limited tumor formation and metastasis have been observed after ASO-mediated downregulation of lncRNA-SChLAP1 (SWI/SNF Complex Antagonist Associated With Prostate Cancer 1), which is upregulated in prostate cancer." (PMID 41551874, 2025).
prostate carcinoma (continued). "It has been shown that aberrant expression of the lncRNA SChLAP1 is associated with the development of lethal prostate cancer, whereas high expression levels of SChLAP1 in prostate cancer tissues are significantly associated with biochemical recurrence, clinical progression, and mortality." (PMID 38605206, 2024). "Similarly, PCAT-18 (prostate-cancer-associated non-coding RNA transcript 18 and SChLAP1 (second chromosome locus associated with prostate-1)) has also been used as a diagnostic and prognostic biomarker in PCa." (PMID 37218885, 2023). "In addition to protein‐coding genes, cribriform prostate cancers often have increased expression of SChLAP1, a long noncoding RNA associated with prostate cancer progression to metastasis." (PMID 33600062, 2021). "Notable examples associated with aggressive cancer and adverse outcomes include HOTAIR (HOX transcript antisense RNA), which is upregulated in a range of cancers, and the prostate cancer-specific SCHLAP1 (SWI/SNF Complex Antagonist Associated With Prostate Cancer 1)." (PMID 33585078, 2021). "The gene of the SWI/SNF complex antagonist associated with prostate cancer 1 (SChLAP1) maps on chromosome 2q31.3 and produces at least seven transcripts; however, more than 90% of these transcripts only belong to four splicing variants of 1.7, 1.4, 1.3 and 1.1 kb." (PMID 29165379, 2017). "Moreover, SChLAP1 expression has also been associated with metastasis (odds ratio [OR] 2.45, 95% CI 1.70–3.53; p-value < 0·0001) and cancer progression (hazard ratio = 1.99, p-value = 0.032) in prostate cancer patients." (PMID 37108589, 2023). "Since it is already considered to be a useful biomarker for predicting metastatic progression in prostate cancer, SChLAP1 is of interest as a promising therapeutic target." (PMID 39975023, 2025). "Since the specific role of SChLAP1 in driving prostate cancer metastasis remains largely unexplored, this study aimed to investigate its structure-function relationship to uncover the underlying mechanism." (PMID 39975023, 2025). "An early study characterized a lncRNA, SChLAP1, which is highly expressed in some prostate cancer patients and was found to be critical for cancer cell invasion and metastasis." (PMID 39408810, 2024). "The MER52A sequence not only contains a functional regulatory promoter for lncMER52A, and the initial exon of lncMER52A also originates from the 3’ terminal of the MER52A element, which is similar to the LTR12C-derived SChLAP1 in prostate cancers." (PMID 38606358, 2024). "Prensner and colleagues identified lncRNA SChLAP1 as a potential biomarker useful to predict metastatic progression in prostate cancer patients treated with radical prostatectomy." (PMID 37143733, 2023). "In the context of prostate cancer, the upregulation of specific lncRNAs, such as UAC1, PVT1, PCA3, HOTAIR, and SChLAP1, has been associated with increased tumor cell growth." (PMID 38067216, 2023). "Within this aberration, we identified the long non-coding RNA SChLAP1 that was reported to be overexpressed in a subset of prostate cancers characterized by aggressive clinical behavior." (PMID 36604606, 2023). "For example, SChLAP1 is a lncRNA whose length is 854 nt, is transcribed from chromosome 2, and is differentially expressed in bladder normal tissue and prostate cancer tissue." (PMID 37108589, 2023). "A high expression of SChLAP1 can be found in approximately 25% of all prostate cancers except for 44% of prostate cancers harboring IDC-P or Gleason pattern 4 of the cribriform type." (PMID 38067216, 2023). "With respect to prostate cancer, there are also related reports, for example, PCA3 and SChLAP1 were reported to be biomarkers for prostate cancer." (PMID 35310913, 2022). "The results reveal high expression of exosomal lncRNA SAP30L-AS1 in BPH, while SChLAP1 shows more expression in prostate cancer compared to BPH." (PMID 35773731, 2022).
prostate carcinoma (continued). "Another experiment investigated expression level of two exosomal lncRNAs including SAP30L-AS1 and SChLAP1 in prostate cancer and BPH." (PMID 35773731, 2022). "These investigations convincingly proved the mediating roles of the miRNA-DNMT3a feedback loop in SChLAP1/EZH2-induced prostate cancer pathogenesis." (PMID 33589600, 2021). "The cheRNA SChLAP1 is highly expressed in prostate cancer, which promotes the invasion and metastasis of prostate cancer cells by antagonizing the SWI/SNF complex and then affecting the localization of nucleosomes." (PMID 33937246, 2021). "In this study, we demonstrated that the overexpression of DNMT3a effectively abrogated the SChLAP1 silencing-induced alterations of prostate cancer cell proliferation, migration, and tumor formation in nude mice, as well as miRNA expressional changes." (PMID 33589600, 2021). "We confirmed here the elevation of SChLAP1 expression in various prostate cancer cells, which was negatively correlated with the expression of miR-340-5p, miR-143-3p, and miR-145-5p." (PMID 33589600, 2021). "We found that SChLAP1 expression was significantly elevated in prostate cancer tissues and cell lines, which was negatively correlated with miR-340 expression." (PMID 33589600, 2021). "LncRNA SChLAP1 contributes to the acceleration on the proliferation and metastasis of prostate cancer via regulating miR-198-mediated MAPK1 pathway." (PMID 31992960, 2020). "SCHLAP1 promotes proliferation and metastasis of prostate cancer by targeting miR-198 and promoting MAPK1 pathway." (PMID 31419958, 2019). "SCHLAP1 is a lncRNA discovered during a bioinformatic analysis carried out to identify lncRNAs selectively upregulated in prostate cancer." (PMID 31366128, 2019). "It has been reported that SCHLAP1 is up-regulated in prostate cancer compared with benign prostatic hyperplasia and normal tissue." (PMID 31419958, 2019). "SChLAP1 promotes prostate cancer invasiveness and metastasis by binding to SWI/SNF and titrating it away from the chromatin." (PMID 29416704, 2018). "One such RNA, SChLAP1, is significantly overexpressed in aggressive prostate cancers and shows promise as a prognostic indicator; this molecule acts to promote metastasis by binding to a tumor-suppressing complex, inhibiting its beneficial properties." (PMID 29723810, 2018). "In prostate cancer, a recent study indicated that miR-198-5p is targeted by the long noncoding RNA SChLAP1, leading to the activation of the MAPK1 pathway, thereby promoting cancer cell proliferation and metastasis." (PMID 29394946, 2018). "As expected, we observed a strong right skewed distribution for SCHLAP1, confirming the reported expression pattern of this gene in prostate cancer." (PMID 28881605, 2017). "For this analysis, we included the well-characterized lncRNA SCHLAP1 as control for high grade prostate cancer." (PMID 28881605, 2017). "In prostate cancer, high expression of the lncRNA SChLAP1 correlates with aggressive tumour phenotypes and metastasis, and experimental evidence suggests that SChLAP1 antagonizes the tumour suppressive functions of the SWI/SNF complex." (PMID 27756687, 2017). "In the same study, it was reported that the SChLAP1 knockdown in prostate cancer cell lines altered their gene expression profile in a way that was contrary to that of the SWI/SNF chromatin-modifying complex." (PMID 29165379, 2017). "We used PCAT1, EZH2, and SChLAP1 as control genes, all of which have elevated expression in prostate cancer metastases." (PMID 24727738, 2014). "By contrast, we have used these datasets to confirm the prognostic utility of the lncRNA SChLAP1 in prostate cancer, and high expression of SChLAP1 is a powerful predictor for poor patient survival." (PMID 24727738, 2014). "Ultimately, this work has significant public health implications in that SChLAP1 could be a novel target for prostate cancer therapeutics." (PMID 39975023, 2025).
prostate carcinoma (continued). "Overall, these data show that both structural modules of SChLAP1 could independently promote prostate cancer cell proliferation." (PMID 39975023, 2025). "Indeed, our functional studies showed that the truncated versions of SChLAP1 contain all the elements necessary to promote the invasion and proliferation of prostate cancer cells." (PMID 39975023, 2025). "Previous research revealed that SChLAP1 could modulate prostate cancer cell invasion and proliferation." (PMID 39975023, 2025). "Moreover, in our study, to test the functional significance we employed two cell lines, 22Rv1 cells, a prostate cancer cell line with low basal SChLAP1 expression, and LNCaP cells, which have high basal SChLAP1 expression." (PMID 39975023, 2025). "Therefore, to examine the potential functional significance of the 5’ and 3’ ends of SChLAP1 in prostate cancer, we overexpressed plasmids containing these regions in parallel with full-length in two cell lines, LNCaP and 22Rv1." (PMID 39975023, 2025). "In prostate cancers, lncRNA SChLAP1 is highly expressed in ∼25% of cancer tissues, and could serve as a potential target for predicting patient outcome." (PMID 38606358, 2024). "Furthermore, the expression of SChLAP1 was found to connect with the progression of prostate cancer that was likely to be fatal." (PMID 39512820, 2024). "It has been shown that SChLAP1 promotes prostate cancer development and may serve as a predictor of poor clinical outcomes." (PMID 39408810, 2024). "Moreover, it has been confirmed that SChLAP1 facilitates prostate cancer progression by interacting with EZH2 to mediate DNA methylation of various miRNAs on chromosome 5 with a DNMT3A-feedback loop." (PMID 38890707, 2024). "Moreover, SChLAP1 improves the invasiveness of prostate cancer cells, and their high levels correlate with tumour aggressiveness." (PMID 38342891, 2024). "Also of interest were several genes associated with prostate cancer metastases including FOXA1, EZH2, SCHLAP1, CDH1, SOX4, SOX9, HOXB13, and TGFBR3." (PMID 38067373, 2023). "These authors showed a non-invasive method to detect SChLAP1 in urine samples suggesting that SChLAP1 could represent a promising biomarker to discern aggressive prostate cancer." (PMID 37143733, 2023). "For instance, SChLAP1 was a lncRNA specifically expressed in prostate cancer cells, which could be used as an effective biomarker in the identification and postoperative observation of prostate cancer." (PMID 33986803, 2021). "Altogether, our results suggest that SChLAP1 enhanced the proliferation, migration, and tumorigenicity of prostate cancer cells through interacting with EZH2 to recruit H2K27me3 and mediate promoter methylation modification of miR-340-5p/miR-143-3p/miR-145-5p with a DNMT3a-feedback loop." (PMID 33589600, 2021). "Also, we proved here that the feedback loop between miR-340-5p/miR-143-3p/miR-145-5p and DNMT3a expression mediated the oncogenic roles of SChLAP1 in prostate cancer development." (PMID 33589600, 2021). "Furthermore, SChLAP1 overexpression inhibited miR-340-5p/miR-143-3p/miR-145-5p expression in prostate cancer cells, which were abrogated by treatments with EZH2, H3K27me3, and DNMT3a inhibitors." (PMID 33589600, 2021). "And SChLAP1/EZH2 could also promote prostate cancer tumor development via the interaction of microRNA-DNMT3a signaling pathways in xenograft nude mice." (PMID 33589600, 2021). "LncRNA SChLAP1 aggravates prostate cancer cell proliferation and metastasis by targeting miR-198." (PMID 32781986, 2020). "Prostate cancer has been associated with over-expression of long intergenic non-protein coding RNA gene SCHLAP1 (SWI/SNF Complex Antagonist Associated with Prostate Cancer 1)." (PMID 30386629, 2018). "SChLAP1 was significantly up-regulated in prostate cancer compared to BPH and normal controls." (PMID 30200254, 2018). "Another example is SChLAP1, which is a lncRNA upregulated in prostate cancer." (PMID 29416704, 2018).
prostate carcinoma (continued). "Similarly SChLAP1, a lincRNA over-expressed in aggressive prostate cancer, interferes with the localization of the chromatin binding SWI/SNF complex." (PMID 28423633, 2017). "In prostate cancer, lncRNAs likewise have diagnostic (e.g., prostate cancer antigen 3, PCA3), prognostic (e.g., second chromosome locus associated with prostate-1, SChLAP1), and predictive (e.g., metastasis-associated lung adenocarcinoma transcript-1, MALAT-1) functions." (PMID 28241429, 2017). "The upregulation of SChLAP1 in PCa patients could lead to poor outcomes, including metastasis and prostate cancer-specific mortality, by antagonizing the tumor-suppressive functions of the SWI/SNF complex." (PMID 28915709, 2017). "Several lncRNAs have been used as diagnostic and prognostic markers, including the following: MALAT-1 for liver, lung, breast, and prostate cancer; HOTAIR for breast, brain, and colon cancer; OOC1 for colon cancer; and PCA3, PCAT-1, and SChLAP1 for prostate cancer." (PMID 26160837, 2015). "For comparison, we used the prostate cancer lncRNA SChLAP1 as a positive control." (PMID 24727738, 2014). "However, the lncRNA SChLAP1 imparts functioning of SWI/SNF complexes contributing to development of lethal prostate cancers." (PMID 25027842, 2014). "We chose the 22Rv1 cell line, a human prostate carcinoma epithelial cell line with low endogenous SChLAP1 expression, making it suitable for overexpression, and LNCaP, an androgen-sensitive prostate adenocarcinoma cell line, which naturally exhibits high SChLAP1 expression." (PMID 39975023, 2025). "To further investigate whether the 5’ and 3’ ends of SChLAP1 regulate the expression of genes involved in prostate cancer cell invasion and proliferation, we examined the expression level of pro-invasion and pro-proliferation genes in LNCaP and 22Rv1 cells upon overexpressing the ends of SChLAP1." (PMID 39975023, 2025). "However, the roles of SChLAP1 in regulating the expression of prostate cancer-suppressing miR-340-5p, miR-143-3p, and miR-145-5p in chromosome 5 remains unknown." (PMID 33589600, 2021). "Consistent with previous research, our RT-qPCR results demonstrated that SChLAP1 knockdown significantly inhibited the expression of invasion markers MMP-9 and MMP-14, as well as the proliferation marker VEGF, in prostate cancer cells." (PMID 39975023, 2025). "The upregulated gene set included oncogenes such as PIK3CB, FGFRL1, and NCOA2; prostate cancer-related genes such as SPON2, PCAT4, and SCHLAP1; and cell cycle genes such as MKI67, MCM4, KIF4A, CENPF, and FLNB." (PMID 38067373, 2023). "For final validation of the function mechanism of SChLAP1/EZH2 in prostate cancer tumorigenesis, we established the CDX model by subcutaneous injection on nude mice with cultured prostate cancer cells." (PMID 33589600, 2021). "For example, we found the pca-lncRNAs SCHLAP1 and PCAT14, both known to be enriched in prostate cancer cells, to exhibit upregulation (logFC = 1.28, FDR = 1.63 × 10−2) and downregulation (logFC = −3.77, FDR = 1.83 × 10−20), respectively, in metastases compared to primary tumors." (PMID 38396008, 2024). "SChLAP1 directly binds with EZH2 and repressed multiple miRNA expression on chromosome 5 including the miR-340-3p in prostate cancer cells through recruiting H3K27me3 to mediate promoter methylation modification of miR-340-5p/miR-143-3p/miR-145-5p to suppress gene transcription." (PMID 33589600, 2021). "Finally, the roles of SChLAP1/EZH2 and the downstream miRNA-DNMT3a loop in prostate cancer pathogenesis were further validated by cellular and animal tumorigenic models." (PMID 33589600, 2021). "SCHLAP1 is not expressed in other cancers or in any normal tissue and is highly overexpressed in patients with aggressive prostate cancer compared to localized prostate cancer." (PMID 31366128, 2019).